SNRPB (small nuclear ribonucleoprotein polypeptides B and B1)
Diseases named in the same sentence as SNRPB in open-access papers (continued):
Sharing a sentence is not in itself a finding about the gene and the disease.
cancer (18 papers, 2012 to 2025). A tumor composed of atypical neoplastic, often pleomorphic cells that invade other tissues. "Recent studies have implicated aberrant SNRPB expression in the pathogenesis of various cancers including lung and cervical cancers, indicating its potential role as a biomarker or therapeutic target in oncology." (PMID 40682115, 2025). "Small Nuclear Ribonucleoprotein Polypeptides B and B1 (SNRPB) have been linked to multiple human cancers." (PMID 38189879, 2024). "In conclusion, our results represent a novel mechanism of how SNRPB is involved in HCC cell survival through the regulation of cancer-related genes." (PMID 39850359, 2025). "For example, splicing factor small nuclear ribonucleoprotein polypeptides B and B1 (SNRPB) is highly expressed in many cancers, including HCC." (PMID 39850359, 2025). "SNRPB is overexpressed in multiple human cancers and modulates multiple processes, such as cell proliferation, migration, invasion, cisplatin resistance and stemness." (PMID 39910288, 2025). "Small nuclear ribonucleoprotein polypeptides B and B1 (SNRPB) has been indicated to be carcinogenic in several cancers; however, its function and mechanism in PTC are unclarified." (PMID 36329787, 2022). "Among the five genes, the mechanism of HMGA1, MPZL1, RACGAP1, and SNRPB in cancer progression were reported in several prior studies." (PMID 35205612, 2022). "Here, the mRNA expression of SNRPB was found to be upregulated in LUAD compared to non-cancer tissues." (PMID 35356432, 2022). "Emerging evidence has suggested that SNRPB overexpression promoted cancer cell proliferation and metastasis." (PMID 33289700, 2020). "SNRPB is a key subunit of the spliceosome that is involved in regulating the alternative splicing of the premRNA, but its role in cancer progression is unclear." (PMID 33289700, 2020). "Of note, SRNPB and RAB26 both showed similar expression trends across different stages of LUAD carcinomas, further corroborating the positive correlation between SNRPB and RAB26 in NSCLC, and which is consistent with our TMA analysis." (PMID 31511502, 2019). "Gene ontology enrichment analysis of gene expression and splicing data revealed that SNRPB influences a large number of biological processes with relevance to cancer, such as RNA processing and DNA repair." (PMID 27287018, 2016). "As one of the SNRP proteins, SNRPB has been shown to act as an oncogene in several cancers." (PMID 36329787, 2022). "Therefore, SNRPB-mediated alternative splicing promotes cancer progression and may be used as a prognostic marker in HCC." (PMID 33289700, 2020). "The role of RBPs in promoting cancer has been confirmed, and DROSHA, EXOSC8, HNRNPC, MRPS31, RPLP2, and SNRPB have also been reported to be related to the occurrence and development of a variety of tumors." (PMID 33981333, 2021).
tumor (13 papers, 2011 to 2025). "Correlation analysis identified key splicing factors, including HSPA8, SNRPB, and hnRNPs, linked to tumor-specific AS events, especially for reduced intron retention." (PMID 40702779, 2025). "Next, we analyzed the splicing events and variants regulated by SNRPB and found that these transcripts with significant differences were associated with the tumor carbon metabolism pathway." (PMID 33289700, 2020). "To figure out the underlying mechanisms responsible for the tumor suppression, we examined the influence of SNRPB knockout on cell proliferation in vivo." (PMID 31511502, 2019). "Using gene expression profiling, we found that SNRPB exhibited a significant upregulation in tumor tissues, in comparison to adjacent normal tissues." (PMID 40682115, 2025). "IHC staining of tumor tissues further revealed that SNRPB overexpression correlated with higher Ki67 expression, indicating enhanced cell proliferation." (PMID 40682115, 2025). "In terms of clinicopathological correlation, CETN2, MPZL1, RACGAP1, and SNRPB were upregulated in patients with microvascular invasion, and the expression of MPZL1 and SNRPB was increased in proportion to the Edmonson tumor differentiation grade." (PMID 35205612, 2022). "SNRPB protein was predominantly nuclear and significantly elevated in tumor tissues compared with normal tissues." (PMID 31511502, 2019). "Putting together, these results indicate that RAB26 is a major target that mediates the role of SNRPB in tumor cell growth and metastasis." (PMID 31511502, 2019). "In addition, an in vivo xenograft tumor assay suggested that knockdown of SNRPB impaired its tumorigenicity." (PMID 33289700, 2020). "Sphere formation in soft agar, foci formation in monolayer culture and tumorigenesis in nude mice indicated that knockdown of SNRPB could suppress tumor cell growth, and SNRPB transfection rescued the proliferation of Hep3B cells." (PMID 33289700, 2020). "Therefore, overexpression of SNRPB promotes HCC malignant progression by facilitating tumor cell growth." (PMID 33289700, 2020). "Despite the need for a more detailed analysis to determine how alterations identified here affect protein function in specific ways to contribute to tumor initiation and growth, we conclude that our data suggest diverse routes by which SNRPB influences GBM development." (PMID 27287018, 2016). "In addition to the factors mentioned, it is likely that other SFs identified here as having consistent changes across all tumor types (SNRPB, RNPS1, RBM34, ELAVL1, and RALYL) could contribute to tumor-associated splicing events in the analyzed datasets." (PMID 33621242, 2021). "Functional analyses demonstrated that the knockdown of SNRPB inhibited HCC cell phenotypes in vitro and suppressed tumor growth in vivo significantly." (PMID 40682115, 2025). "The combined treatment group showed an intermediate tumor weight, suggesting that CCNB1 knockdown partly mitigates the tumor-promoting effect of SNRPB overexpression." (PMID 40682115, 2025). "Overexpression of SNRPB in H460 cells markedly facilitate xenograft tumor growth and metastasis, however, knockout of RAB6 attenuated SNRPB-induced tumor growth and metastasis." (PMID 31511502, 2019). "Therefore, characterizing the downstream effects of SNRPB dysregulation in HCC, such as alterations in gene expression profiles or cellular processes, could provide a comprehensive understanding of its impact on tumor biology." (PMID 40682115, 2025).
SNRPB also shares sentences with these, for which no sentence is quoted: hepatocellular carcinoma (3 papers); autoimmune (2); autoimmune disease (2); breast invasive carcinoma (1); Burn–McKeown syndrome (1); campomelic dysplasia (1); Catel-Manzke syndrome (1); colon adenocarcinoma (1); craniofacial microsomia (1); esophageal carcinoma (1); genetic disease (1); Glass syndrome (1); Macrocephaly (1); mandibulofacial dysostosis (1); Micrognathia (1); mixed connective tissue disease (1); Nager syndrome (1); ocular hypertelorism (1); SARS-CoV Infections (1); scoliosis (1); Stickler syndrome (1); stomach adenocarcinoma (1); Verheij syndrome (1).